TMA7B (translation machinery associated 7 homolog B)
Gene: Protein-coding gene on chromosome 22 (39,960,397 to 39,964,905, forward strand). Ensembl gene ENSG00000225528.
Subcellular location (Human Protein Atlas): Nucleoli; Nucleoli rim; Nuclear bodies; Nucleoplasm
Homologues: Paralogues in human: TMA7 (89% identical).